DMAP1 (DNA methyltransferase 1 associated protein 1)
Description:
Involved in transcription repression and activation. Its interaction with HDAC2 may provide a mechanism for histone deacetylation in heterochromatin following replication of DNA at late firing origins. Can also repress transcription independently of histone deacetylase activity. May specifically potentiate DAXX-mediated repression of glucocorticoid receptor-dependent transcription. Component of the NuA4 histone acetyltransferase (HAT) complex which is involved in transcriptional activation of select genes principally by acetylation of nucleosomal histones H4 and H2A. This modification may both alter nucleosome - DNA interactions and promote interaction of the modified histones with other proteins which positively regulate transcription. This complex may be required for the activation of transcriptional programs associated with oncogene and proto-oncogene mediated growth induction, tumor suppressor mediated growth arrest and replicative senescence, apoptosis, and DNA repair. NuA4 may also play a direct role in DNA repair when recruited to sites of DNA damage. Participates in the nuclear localization of URI1 and increases its transcriptional corepressor activity.
Synonyms: DNMAP1; KIAA1425; FLJ11543; DNMTAP1; EAF2; MEAF2; SWC4
Tractability: Small molecule: a structure with a bound ligand is known. PROTAC: UniProt records ubiquitination sites on it; ubiquitination databases record sites on it; its protein half-life has been measured.
Gene: Protein-coding gene on chromosome 1 (44,213,427 to 44,220,681, forward strand). Ensembl gene ENSG00000178028.
Subcellular location: Nucleus; Cytoplasm
Subcellular location (Human Protein Atlas): Nucleoplasm; Cytosol
Pathways (Reactome):
Chromatin organization: HATs acetylate histones
Gene Ontology:
Molecular function: protein binding; RNA polymerase II-specific DNA-binding transcription factor binding; transcription corepressor activity
Biological process: negative regulation of transcription by RNA polymerase II; positive regulation of double-strand break repair via homologous recombination; positive regulation of protein import into nucleus; regulation of cell cycle; chromatin remodeling; negative regulation of DNA-templated transcription; positive regulation of DNA-templated transcription; regulation of apoptotic process; regulation of DNA-templated transcription; regulation of double-strand break repair; DNA repair; response to ethanol
Cellular component: cytoplasm; cytosol; NuA4 histone acetyltransferase complex; nucleoplasm; nucleosome; nucleus; chromosome; replication fork
Genetic constraint (gnomAD): Loss-of-function variants: 26 observed, 52.21 expected, observed/expected ratio (o/e) 0.5, 90% interval 0.36 to 0.69. The upper end of that interval is the gene's LOEUF score, 0.69, which puts it in group 2 of 6, group 1 being the genes least tolerant of losing a copy. Missense variants: 439 observed, 616.72 expected, observed/expected ratio (o/e) 0.71, 90% interval 0.66 to 0.77. Synonymous variants: 231 observed, 244.01 expected, observed/expected ratio (o/e) 0.95, 90% interval 0.85 to 1.06.
Homologues: Orthologues: chimpanzee DMAP1 (100% identical), macaque DMAP1 (100% identical), dog DMAP1 (99% identical), pig DMAP1 (99% identical), rat Dmap1 (99% identical), mouse Dmap1 (98% identical), guinea pig DMAP1 (91% identical), tropical clawed frog dmap1 (83% identical), zebrafish dmap1 (79% identical), rabbit DMAP1 (76% identical), Drosophila melanogaster DMAP1 (44% identical), Caenorhabditis elegans ekl-4 (37% identical).
Diseases named in the same sentence as DMAP1 in open-access papers:
DMAP1 is named in the same sentence as 17 diseases in open-access papers, as found by Europe PMC text mining. Sharing a sentence is not in itself a finding about the gene and the disease. The quoted sentences say what the papers report.
pancreatic cancer (4 papers, 2018 to 2023). "Hyperaction of c-Src has been importantly implicated in pancreatic cancer progression, the positive impacts of c-Src-mediated DMAP1 pY246 on tumour growth exemplifies that the adaption of cancer cells to mitotic defect-induced stress is addicted to strong c-Src activity." (PMID 30553276, 2018). "DMAP1 was highly phosphorylated in pancreatic cancer cells, which impeded DMAP1/BUB3 interaction and the relevant cellular activity." (PMID 36787437, 2023). "Here, we show DMAP1/Bub3 complex mediates mitotic stress-induced cellular apoptosis, while this effect is counteracted by c-Src in pancreatic cancer cells." (PMID 30553276, 2018). "In pancreatic cancer cells, DMAP1 is highly phosphorylated by c-Src; this phosphorylation abrogates DMAP1/Bub3 complex formation under mitotic arrest and eventually maintains cell survival." (PMID 30553276, 2018). "Clinically, DMAP1 Tyr 246 phosphorylation correlates with c-Src activity in human pancreatic cancer specimens and poor prognosis in pancreatic cancer patients." (PMID 30553276, 2018). "Our findings reveal a regulatory role of Bub3 in DMAP1-mediated DNA methylation upon mitotic stress and provide the relevance of DMAP1 pTyr-246 to mitotic stress resistance during pancreatic cancer treatment." (PMID 30553276, 2018). "Meanwhile, DMAP1 was highly phosphorylated at Tyr 246 by c-Src in pancreatic cancer cells, which impedes DMAP1/Bub3 interaction and the relevant cellular activites." (PMID 30553276, 2018). "In a Cox multivariate model, the IHC scores of DMAP1 Y246 phosphorylation is an independent predictor of pancreatic cancer patient survival after adjusting for the age of the patient." (PMID 30553276, 2018). "In our study, we found pancreatic cancer cells display high level of DMAP1 pY246 mediated by c-Src; and this blocks mitotic arrest-induced Bub3/DMAP1 interaction and thus protects cancer cells from mitotic arrest-induced apoptosis." (PMID 30553276, 2018). "Subsequently, Bub3/DMAP1 interaction was examined in pancreatic cancer cell PANC-1 cells and SW1990 cells." (PMID 30553276, 2018). "To further define the clinical relevance of our finding, we first examined the c-Src activity and DMAP1 pY246 by immunoblotting of tissue extracts from 8 human pancreas tumour specimens." (PMID 30553276, 2018). "DMAP1 is highly phosphorylated by c‐Src in pancreatic cancer cells." (PMID 34882895, 2022). "Indeed, this is supported by clinical analysis showing that the level of DMAP1 pY246 generally correlates to poor prognosis of pancreatic cancer patient." (PMID 30553276, 2018). "In addition, IHC analyses were performed to examine DMAP1 pY246 levels in serial sections of 90 human pancreas tumour specimens." (PMID 30553276, 2018).
colorectal cancer (3 papers, 2020 to 2023). A primary or metastatic malignant neoplasm that affects the colon or rectum. "The three-hit model has shown to be applicable in APC in colorectal cancer, and it can be speculated whether this same model could be applicable for YEATS4 and DMAP1 in case of mutations with possible residual activity." (PMID 36773604, 2023). "Lee and colleagues reported that DMAP1 knockdown in colorectal cancer cells could slow and finally ceased cell growth, which may be because the low DMAP1 reactivated some tumor suppressive genes by reducing their CpGs methylation." (PMID 34834420, 2021).
neuroblastoma (2 papers, 2020 to 2021). Neuroblastoma (NB) is the most common solid, extracranial childhood tumor.
polycystic ovary syndrome (2 papers, 2018 to 2020). A disorder that manifests as multiple cysts on the ovaries. "Recently, Kokosar and colleagues reported that Dmap1 was heterogeneously expressed in adipose tissue in women with polycystic ovary syndrome (PCOS), which resulted in the epigenetic and transcriptional alternations." (PMID 32403252, 2020).
breast carcinoma (1 paper, 2021). "We next explored the clinical and bio-functional effect of the transcription factor DMAP1 in breast cancer." (PMID 34834420, 2021). "We used real world and network data to confirm that the expression of DMAP1 decreased in breast cancer tumors compared with normal tissues." (PMID 34834420, 2021). "DNA Methyltransferase 1 Associated Protein 1 (DMAP1) was among the 13 TFs in our study, and it has been rarely studied in breast cancer, so we focused on it for further analysis." (PMID 34834420, 2021). "We also focused on the transcription factor DMAP1 because research into this gene in breast cancer is scarce." (PMID 34834420, 2021). "We first explored the expression of DMAP1 in breast cancer, tumor adjacent tissues, and normal tissues in the GTEx and TCGA datasets." (PMID 34834420, 2021). "The PAM50 subtypes of breast cancer showed that the DMAP1 expression was higher in luminal subtypes than in the basal-like and HER2-amplified subtypes." (PMID 34834420, 2021). "In this study, we used quantitative proteomic analyses of nuclear proteins and massive transcriptome data to identify enriched potential TFs and explore the possible role of the transcription factor DMAP1 in breast cancer." (PMID 34834420, 2021). "The data shows that the DMAP1 expression was negatively correlated with most infiltration immune cell types, not only in breast cancer but also in other solid tumors, which revealed its universal application in tumors." (PMID 34834420, 2021). "DMAP1 also showed survival predictive value for breast cancer patients." (PMID 34834420, 2021). "In our study, we found that DMAP1 also had a tumor-suppressive function in breast cancer." (PMID 34834420, 2021). "As the DMAP1 expression level could identify distinct immune features in breast cancer, we next studied the relationship between tumor-infiltrating lymphocytes (TILs) and the expression of DMAP1 in solid pan-cancers of the TCGA dataset." (PMID 34834420, 2021). "However, among these 13 TFs, we noticed that the transcription factor DMAP1 has seldom been reported in breast cancer." (PMID 34834420, 2021). "The network showed that some commonly used chemotherapy agents for breast cancer could affect DMAP1 gene expression." (PMID 34834420, 2021). "The results showed that DMAP1 expression was negatively correlated with most immune features in the majority of solid tumors; these results were consistent with our previous findings in breast cancer." (PMID 34834420, 2021). "The expression of DMAP1 decreased in breast cancer tumors compared with normal tissues." (PMID 34834420, 2021). "Among the 13 TFs in our study, DMAP1 has been the least reported in breast cancer." (PMID 34834420, 2021). "All these findings indicate that DMAP1 may be used as a tumor suppressor in breast cancer." (PMID 34834420, 2021). "As DMAP1 is involved in DNA methylation, we suspect that it may influence the methylation of some genes and then their expression to play its inhibitory role in breast cancer." (PMID 34834420, 2021). "As DMAP1 is also named Dnmt1-associated protein 1, and it has a binding role and a potent activation role in DNMT1 methylation, we speculate that DMAP1 may control the biological properties of breast cancer through its gene methylation ability." (PMID 34834420, 2021). "The reason why low expression of DMAP1 was correlated with poor prognosis in breast cancer is not clear, but the bioinformatic analysis between high and low expression of DMAP1 revealed some clues." (PMID 34834420, 2021). "The correlation of DMAP1 and molecular typing markers for breast cancer showed that DMAP1 expression was lower in ER negative, PR negative, and HER2 positive subtypes, as well as in tumors with high Ki67 expressed." (PMID 34834420, 2021). "The low DMAP1 group showed high activation of the PI3K/Akt signaling pathway; thus, blocking the PI3K-AKT pathway may be helpful for these breast cancer patients." (PMID 34834420, 2021).
gastric cancer (1 paper, 2021). A primary or metastatic malignant neoplasm involving the stomach.
hepatoma (1 paper, 2013). "It has been previously shown that in HLE cells (human hepatoma cell line) DMAP1 binds URI and dictates its nuclear translocation, possibly masking a cytoplasmic localization sequence in the second α-helix of the URI prefoldin-like domain." (PMID 23667685, 2013).
lung carcinoma (1 paper, 2026). "Clinical data analyses revealed that high DMAP1 expression is associated with a "cold" tumor microenvironment and poorer overall survival in lung cancer." (PMID 41904944, 2026). "Through a CRISPR-based knock-out screen, we identified the DNA methyltransferase 1-associated protein 1 (DMAP1) as a critical regulator of lung cancer progression." (PMID 41904944, 2026).
melanoma (1 paper, 2021). A malignant, usually aggressive tumor composed of atypical, neoplastic melanocytes. "Of the other six significant genes identified in the screen (TRIM28, CDYL2, DMAP1, CBX5, PYGO2), TRIM28 is known to increase melanoma tumor propagation potential." (PMID 33527896, 2021).
type 2 diabetes (1 paper, 2016). "Six out of twenty selected genes with largest expression difference (CYP1B1, GPT), genes linked to PCOS (RAB5B) or type 2 diabetes (PPARG, SVEP1), and methylation (DMAP1) were replicated in a separate case-control study." (PMID 26975253, 2016).
tumor (11 papers, 2007 to 2026). "Functional studies demonstrated that DMAP1 deficiency exerts its anti-tumor effects through attenuating tumor cell proliferation and activating T cell-mediated adaptive anti-tumor effects." (PMID 41904944, 2026). "The number of ULs varied from one to four in individuals with a DMAP1 germline variant, and the size of the largest tumor ranged from 32 mm to 97 mm." (PMID 36773604, 2023). "As both the online database and our own data show, the expression of DMAP1 was lower in tumor tissues than in non-tumor tissues, and analysis of the large amount of data indicated that low expression of DMAP1 was associated with poor survival outcomes." (PMID 34834420, 2021). "The Mat1-mediated transcriptional repressor (MMTR)/DNA methyltransferase 1 (DNMT1)-associated protein (Dmap1) is a transcription corepressor involved in chromatin remodeling, cell cycle regulation, DNA double-strand break repair, and tumor suppression." (PMID 32403252, 2020). "In our study, we analyzed the relationship between DMAP1 expression and the tumor immune micro-environment." (PMID 34834420, 2021). "The mRNA levels showed that the expression of DMAP1 was significantly the highest in normal tissues, second in tumor adjacent tissues, and lowest in tumor tissues." (PMID 34834420, 2021). "c-Src-mediated DMAP1 Y246 phosphorylation promotes tumour cell survival through inhibition of Bub3/DMAP1 interaction under mitotic arrest." (PMID 30553276, 2018). "Above all, these results suggest Bub3/DMAP1 complex act as a repressive modulator of transcription for anti-apoptotic genes under mitotic stress and its effect is impaired in tumour cells with high levels of DMAP1 pY246." (PMID 30553276, 2018). "Collectively, these data indicated the inhibitory effect of DMAP1 Y246 phosphorylation on Bub3/DMAP1 interaction promoted tumour development." (PMID 30553276, 2018). "As a result, DMAP1 pY246 levels were generally increased along with elevated c-Src/c-Src pY416 levels in tumour tissues compared with the normal counterparts." (PMID 30553276, 2018). "Mechanistically, DMAP1 deficiency causes replication fork retardance, disturbs genome stability, and induces endogenous DNA damage, thereby activating IFN signaling-mediated anti-tumor immune response." (PMID 41904944, 2026). "We next used PCR to analyze the expression of DMAP1 in 19 pairs of matched carcinomas and tumor adjacent tissues from surgical patients at our hospital and found that DMAP1 was expressed significantly lower in carcinoma tissues than in paracarcinomas tissues (p < 0.0001)." (PMID 34834420, 2021). "In other studies, DMAP1 was found to play a tumor-suppressive gene function." (PMID 34834420, 2021). "Our data indicate that the specific inhibition of the DNMT1/DMAP1 interaction acts as a tumor suppressor-like event since the disruption of the DNMT1/DMAP1 interaction increased TMZ + irradiation-induced cell death without promoting the initiation and progression of tumorigenesis." (PMID 23809695, 2013). "In addition, Dmap1 is involved in the DNA double-strand break repair and tumor suppression." (PMID 32403252, 2020). "Patients whose tumours had low DMAP1 pY246 levels (29 cases) had a median survival that was not reached; those whose tumours had high DMAP1 pY246 levels (61 cases) had significantly lower median survival duration of 10.5 months." (PMID 30553276, 2018). "In contrast, a peptide disrupting the DNMT1/DMAP1 interaction, which per se did not affect tumor growth, sensitized cancer cells to chemotherapy/irradiation-induced cell death." (PMID 23809695, 2013). "DMAP1 is known to form a complex with DNMT1 and repress transcription in tumor cells." (PMID 23049944, 2012).
cancer (3 papers, 2013 to 2021). A tumor composed of atypical neoplastic, often pleomorphic cells that invade other tissues. "The genes enriched in the low DMAP1 expression group showed pathways in cancer as well as the PI3K/Akt signaling pathway." (PMID 34834420, 2021). "Unexpectedly, mitotic arrest only led to a slight increase of DMAP1/Bub3 interaction in cancer cells, implying certain cancer-specific signaling participate in the regulation of Bub3/DMAP1 complex formation." (PMID 30553276, 2018). "In consistence to this, our data indicates DMAP1 pY246 facilitates transcription of antiapoptotic-gene BCL2L1 under mitotic arrest in cancer cells, which is linked to its negative effects on Bub3 pS211-mediated DNA methylation at BCL2L1promoter." (PMID 30553276, 2018). "Our findings reveal Bub3/DMAP1 complex is crucial for responsive gene expression following mitotic arrest and demonstrate the survival advantage of cancer cells under mitotic stress is addicted to the inhibitory effect of c-Src on Bub3/DMAP1-mediated apoptosis." (PMID 30553276, 2018). "Our data suggest that the DNMT1/DMAP1 interaction could be an effective anti-cancer target and opens a new avenue for the development of new strategies to design DNMT inhibitors." (PMID 23809695, 2013). "These pathway analyses indicated that low DMAP1 expression may be involved in cancer progression." (PMID 34834420, 2021). "KEGG enrichment analysis also confirmed that in the high DMAP1 expression group, the genes in the PI3K-Akt signaling pathway, the MAPK signaling pathway, and some cancer related pathways had high methylation but low expression." (PMID 34834420, 2021). "According to the KEGG analysis, genes with high methylation levels in the high DMAP1 expression group were enriched in the PI3K-Akt signaling pathway, as well as some cancer related pathways in both cohorts." (PMID 34834420, 2021). "The poor prognosis of patients with low DMAP1 expression may relate to the activated PI3K/Akt signaling pathway, as well as other cancer-relevant pathways." (PMID 34834420, 2021). "The poor prognosis of patients with low DMAP1 expression may be related to the activated PI3K/Akt signaling pathway, as well as other cancer relevant pathways, and this may be because of the low methylation and high expression of genes in this pathway." (PMID 34834420, 2021).
DMAP1 also shares sentences with these, for which no sentence is quoted: glioma (2 papers); coronary heart disease (1); glioblastoma (1); nasopharyngeal carcinoma (1); Obesity (1).